SPNS2 (SPNS lysolipid transporter 2, sphingosine-1-phosphate)
Diseases named in the same sentence as SPNS2 in open-access papers (continued):
Sharing a sentence is not in itself a finding about the gene and the disease.
cancer (continued). "The characterization of Spns2’s function in cancer will not only expand our understanding of S1P delivery and function, but may also contribute to designing new therapeutic strategies to prevent and treat LC." (PMID 25330231, 2014). "Regulating SPNS2 activity may help to treat cancer, inflammation and immune diseases." (PMID 38429907, 2024). "Similarly, SPNS2 has been shown to deliver S1P to S1PR2, leading to increased epidermal growth factor (EGF)-mediated cancer cell invasion, suggesting that SPNS2 inhibitors may be useful therapeutics for cancer treatment." (PMID 35565311, 2022). "Thus, the effect of SPNS2 on cancer progression is complicated and may be dependent on the types of cancer and microenvironments." (PMID 34249729, 2021). "Importantly, although Spns2 mutation did not affect the initial dissemination and extravasation of cancer cells, an increased number of apoptotic cancer cells were observed in the lung." (PMID 28209174, 2017). "In these studies, exposure to hypoxia upregulated Sphk1 to produce iS1P, which was exported by Spns2 to allow a subsequent autocrine action via S1P1, to stabilize HIF-1/2α and thereby drive a more aggressive cancer phenotype." (PMID 35682566, 2022). "However it remains unclear whether Spns2 plays a role in tumorigenesis and cancer progression." (PMID 25330231, 2014). "Thus, siRNA knockdown of S1P1 and Spns2 blocks HIF2α accumulation, suggesting that S1P might exert so-called ‘inside-out’ signaling, where SK1 catalyses formation of S1P, which is released from cells to act on S1P1 in an autocrine manner to regulate cancer cell growth." (PMID 28241498, 2017).
infection (1 paper, 2020). The state of being infected such as from the introduction of a foreign agent such as serum, vaccine, antigenic substance or organism. "The down-regulation of Spns2 in EC might be an effective response to support the infiltration of leukocytes at sites of local infection." (PMID 32290092, 2020).
SPNS2 also shares sentences with these, for which no sentence is quoted: Arthritis (3 papers); experimental autoimmune encephalomyelitis (3); hepatocellular carcinoma (2); metastatic melanoma (2); allergic asthma (1); autoimmune (1); cervix adenocarcinoma (1); choroid plexus papilloma (1); clear cell renal cell carcinoma (1); cystic fibrosis (1); endothelial dysfunction (1); gastric cancer (1); Hearing impairment (1); Hypertension (1); immune diseases (1); inflammation (1); kidney diseases (1); lung adenocarcinoma (1); Lung squamous cell carcinoma (1); Oral Squamous Cell Carcinoma (1); psoriasis (1); rectum adenocarcinoma (1); Usher syndrome (1).